FOXA1 (forkhead box A1)
Diseases named in the same sentence as FOXA1 in open-access papers (continued):
Sharing a sentence is not in itself a finding about the gene and the disease.
cancer (continued). "Overall, we hypothesize that Hypo-MS4 surrogates FOXA1 activity to modulate the cancer methylome, hence interfering with neoantigen presentation and subsequent immune responses in the microenvironment." (PMID 38566132, 2024). "Interestingly, we found that FOXA1 is one of the top-ranking TFs with motifs enriched and is highly expressed in the different cancer cells." (PMID 39383000, 2024). "This demonstrates that the NR3C1 repression via FOXA1 could be a widespread mechanism to restrict GR activity in cancers." (PMID 38015476, 2024). "In addition, the pan-cancer analysis suggests that the activation of these three pathways is also significantly correlated with FOXA1 in other cancer types." (PMID 39440050, 2024). "Here, FOXA1 plays a role in inhibiting cancer cell metastasis and EMT signatures." (PMID 38605023, 2024). "Finally, the proposed method identified a subnetwork that included a well-known cancer gene FOXA1 and four genes from the Vitamin D receptor pathway, which suggests a potentially functional connection." (PMID 37627118, 2023). "FOXA1 is a luminal-lineage TF; therefore, decreasing the accessibility of these elements may result in the dedifferentiation of luminal cancer cells into a basal or mesenchymal state, leading to endocrine resistance and metastasis." (PMID 36725920, 2023). "These publications support the possibility that FOXA1 regulation is cancer and cell‐type specific." (PMID 37491794, 2023). "Therefore, we propose that FOXA1 is one of the key players responsible for the reprogramming of the SRR124–134 cluster in cancer, which then drives SOX2 overexpression in breast and lung tumors." (PMID 37738673, 2023). "It has been shown that low expression of FOXA1 can increase malignancy and cancer stemness." (PMID 36836779, 2023). "FOXA1 had also been reported to play a role in a variety of cancers." (PMID 35184697, 2022). "Finally, both LINC00847 and CTD -2566J3.1 were co-expressed with essential genes for cancer genetic dependencies, such as FOXA1 y GINS2." (PMID 36359853, 2022). "FOXA1 binds approximately 90% of the total different genes available in the human cancer genome." (PMID 35879772, 2022). "However, only around 17% of this FOXA1 involves in transcriptional regulation of genes and these functional FOXA1 are specific to types of cancer cell." (PMID 35879772, 2022). "In the study, we first explored the pan-cancer features of FOXA1." (PMID 36393971, 2022). "To test this, we used CRISPR/Cas9 to knockout (KO) FOXA1 or GATA3 in HCC1954 cancer cells." (PMID 35331302, 2022). "The results revealed that EMT-related pathways was positively correlated with FOXA1 in pan-cancer." (PMID 36393971, 2022). "The role of FOXA1 in AR signalling appears to change during cancer development and progression." (PMID 37435460, 2022). "FOXA1, a member of the Forkhead family of winged-helix transcription factors, has been mainly reported for its role in the regulation of development and differentiation in several organs as well as its participation in cancer." (PMID 36064451, 2022). "On the other hand, researchers also pointed out that FOXA1 might suppress tumorigenesis in some cancer types by inhibiting EMT." (PMID 36393971, 2022). "The gray background indicates that FOXA1 strikingly differs among cancer types." (PMID 35968505, 2022). "Concordantly, differences in FOXA1 and FOXA2 mutational spectra in cancer are striking." (PMID 35703180, 2022). "FOXA1 (HNF3A) is a TF involved in embryonic development which plays an important role in cancer." (PMID 34986601, 2022). "Activity of FOXA1 and ER transcription factors is known to promote pro-metastatic outcomes in HR+ cancer cells, but it remains unknown whether this function is maintained in human tumors in vivo." (PMID 34922480, 2021). "It has been reported that FOXA1 is overexpressed in prostate, esophageal and lung cancer." (PMID 33669586, 2021).
cancer (continued). "FOXA1 has been found to regulate estrogen receptor binding as well as AR and GR binding in both normal and cancer cells." (PMID 34227937, 2021). "FOXA1 is a transcription factor which has important functions in cancer development." (PMID 34911544, 2021). "Herein, we have detailed our strategy for editing FOXA1 in the polyploid cancer cell line MCF‐7." (PMID 33666335, 2021). "Interestingly, for the 33 cancer types from the TCGA Pan-Cancer analysis project, up to 19, 16, and 16 cancer types displayed positive correlations for FOXA1 vs. VPS53, FOXA1 vs. FAM57A, and FOXA1 vs. GEMIN4, respectively." (PMID 34445492, 2021). "Moreover, PC3 separated cancers harboring truncal mutations in SPOP and FOXA1 from the ones harboring gene fusions involving ETS family transcription factors 25–28." (PMID 34857732, 2021). "We first investigated the expression pattern of FOXA1 in TCGA pan-cancer data." (PMID 32929382, 2020). "In luminal cancers, the ER-dependent programs are influenced by pioneer factors FOXA1 and GATA3 and thus genes whose promoters contain binding sites or clusters of sites for these factors may be expected to be dependent on ER programs." (PMID 32987805, 2020). "We hypothesized that lncRNAs resulting from FOXA1 overexpression could also play a vital role in the development of the indicated cancers." (PMID 32929382, 2020). "transcription factors AP-1, NF-κB, STAT3, GR, PR, and FOXA1/2 are inducible in nature and their aberrant expression and constitutive activation play an independent role in carcinogenic inflammation, transformation and maintenance of cancer stemness." (PMID 33344262, 2020). "We interrogated FOXA1 expression levels across cancer types." (PMID 31974375, 2020). "FOXA1 can bind to the promoters of more than 100 genes to influence signaling pathways and cell cycle in human cancers, while its specific mechanism in CRC cells resistant to radiotherapy remains largely unknown." (PMID 32293494, 2020). "Reports on the role of FOXA1 in cancer have been controversial." (PMID 32655839, 2020). "Considering the proposed co-regulatory relationship between KDM3A, KDM4B, and FOXA1, which facilitates a cancer phenotype in ER-positive BC, these data together suggest that targeting KDM3A and KDM4B simultaneously may be an efficacious therapeutic strategy." (PMID 31390833, 2019). "Coupled with the finding that KDM4B also regulates KDM3A expression and that KDM3A regulates both KDM4B and FOXA1 deposition at ER cis-regulatory sites, our data suggests a potential co-regulatory relationship between all three proteins to facilitate a cancer phenotype in ER-positive BC." (PMID 31390833, 2019). "Thus, our data strongly suggest that GATA2 and c‐JUN are TFs in addition to FOXA1 and HOXB13 that associate with ARBSs and regulate AR binding selectively in normal and cancer cells." (PMID 31520575, 2019). "Thus, enhancer–promoter loops not only lead to increased FOXA1 expression, but the upregulated FOXA1 protein then also contributes to the cancer transcriptome by mediating many additional enhancer–promoter loops which lead to increased gene expression." (PMID 31515496, 2019). "In our cohort, 43% of the carcinomas contained FOXA1-positive neoplastic cells." (PMID 31888566, 2019). "Of these primary cancers, 75% were classified into seven subtypes, defined by either specific gene fusions of ETS transcription family members (ERG, ETV1, ETV4, and FLI1) or mutations (SPOP, FOXA1, and IDH1)." (PMID 29581876, 2018). "FOXA1-mutant cancers share similar molecular features with SPOP-mutant cancers." (PMID 29581876, 2018). "However, it appears likely that FoxA1/2 regulate gastrointestinal differentiation programs in other types of cancer." (PMID 30475207, 2018).
cancer (continued). "Since the SD range in consideration with mean value was relatively wider in ER-negative than in ER-positive tumors, and most samples with high AR mRNA levels exhibited high FOXA1 expression in ER-positive cancers; therefore, the correlation coefficient was higher in ER-negative tumors." (PMID 29137314, 2017). "AR and FOXA1 mRNA levels were significantly higher in ER-positive than in ER-negative tumors and AR-low/FOXA1-low tumors showed high grade, frequent basal-like subtype and worse disease-free survival in ER-positive cancers of public gene dataset, similarly to patient cohort results." (PMID 29137314, 2017). "Possibly, FOXA1 is a universal target of the SNAIL family in a wide range of cancer cell types." (PMID 29155818, 2017). "Further investigations into the analysis of molecular interaction within the overall ‘tumorigenic program', as performed for the Foxa1 shown in our data, should allow identification and testing of additional potential candidate molecules involved in cancer development and progression." (PMID 27468690, 2016). "Also, a large number of FOXA1 modulators that can affect proliferation were found and future studies will have to assess their contribution to driving the cancer phenotype." (PMID 27997592, 2016). "FOXA1 may be a particularly relevant therapeutic target since cancers that have become resistant to hormone treatment may still be dependent on FOXA1 for proliferation." (PMID 27997592, 2016). "Interestingly, cancer cell proliferation was impaired in vitro upon depletion of either FoxA1 or FoxA2 in MCF7 and MDA231 cells, respectively." (PMID 27045898, 2016). "Little is known about the ratio of FOXA1 to FOXA2 in cancer." (PMID 26658322, 2015). "Mutations in other genes that may be functionally relevant were noted, especially the recently reported high confidence cancer drivers FOXA1 and CCAR1." (PMID 24823478, 2014). "In addition, a subset of both cancer types exhibit amplification of the genomic region encompassing the FOXA1 gene." (PMID 23420418, 2013). "Thus, Foxa1 and its targets constitute a regulatory feed-forward loop, which likely contributes to Foxa1 function in ER-dependent cancers." (PMID 22737085, 2012). "In addition, we report the loss of FOXA1 expression in KSM and in SCC of the urinary bladder, and show that reduced FOXA1 expression promotes RT4 xenograft proliferation." (PMID 22590586, 2012). "In addition to regulating FOXA1, super-enhancers may also be involved in processes such as glucose metabolism, lipid metabolism, and amino acid metabolism, thereby driving cancer cell adaptation to extreme microenvironments." (PMID 41330917, 2025). "Thus, it is predicted that the deletions we found in this study will also deregulate FOXA1 activity, and that may drive cancer." (PMID 41009328, 2025). "Consequently, increased FOXA1 expression may correlate with the adverse outcomes of malignant tumors." (PMID 39440051, 2024). "However, the role of the FOXA1 to FOXA2 transition in regulating cancer lineage plasticity remains unclear." (PMID 38851846, 2024). "Moreover, our analysis of TCGA data suggests that FOXA1 may also function as a regulator of PD-L1 expression in additional cancer subtypes including squamous cancers of the lung and head and neck." (PMID 36323682, 2022). "Thus, RAMP2.AS1/miR-30b-5p/ESR1 and RAMP2.AS1/miR-30b-5p/FOXA1 axes might be involved in the pathogenesis of this kind of cancer." (PMID 34094972, 2021). "In addition, the authors observed that specifically targeted knockdown of FOXA1 results in the abrogation of both ER chromatin binding and estrogen-induced gene expression, indicating that FOXA1 is required for the accomplishment of estrogen action in cancer cells." (PMID 33925807, 2021). "The association between the expression of FASN and FOXA1 in cancer has not been examined." (PMID 32103349, 2020). "Therefore, we next investigated the role of FOXA1 in regulating the cancer transcriptome." (PMID 31515496, 2019).
cancer (continued). "However, the precise role of FOXA1 in cancer development is controversial." (PMID 26934447, 2016). "Therefore, FOXA1 may be one of the important early events in ER pathway activation, setting the stage for subsequent cancer development." (PMID 24887547, 2014). "Furthermore, the search for known binding factors revealed a significant overrepresentation of binding sites for the E2f family and for FoxA1 (P = 0.01), the former known to contribute to hematopoiesis, the latter known to be involved in normal and cancer development." (PMID 24944583, 2014). "The fact that a minority of lymph node metastases were negative for FOXA1 may indicate that cancer dissemination to lymph nodes occurs prior to loss of FOXA1 within the primary tumor." (PMID 22590586, 2012). "As we mentioned in the previous treatment section, Tel has been confirmed to down-regulate the expression of FOXA1 through the IGF1-R/AKT/FOXA1 pathway, to inhibit the proliferation of cancer cells in ER-positive breast cancer." (PMID 40003882, 2025). "Immunohistochemistry (IHC) analysis of FOXA1, HNF4A and HNF4G from primary PDAC tissue samples confirmed coexpression of these transcription factors, only in the cancer epithelial cells." (PMID 41168397, 2025). "Our findings underscore the FOXA1/BMI1 axis as a key target for NPC treatment, offering insights into a potential new approach to improve patient outcomes in this aggressive cancer." (PMID 40623983, 2025). "The results showed that cancer cell marker genes, such as CDH1, EPCAM, FOXA1, and GATA3, were enriched within the spatial domain (sections (−120, −90], (−90, −60], (−60, −30] and (−30, 0])." (PMID 39965034, 2025). "Next, to directly explore the role of FOXA1 and/or HNF4G in metastasis, engineered human cancer cell lines (HPAF-II) were injected into the tail vein of mice to directly assess metastatic potential." (PMID 41168397, 2025). "The current study explores the intricate relationship between Forkhead Box A1 (FOXA1) and B-cell-specific Moloney murine leukemia virus integration site 1 (BMI1) in the cancer progression and chemoresistance of NPC." (PMID 40623983, 2025). "Although the decrease in expression of FOXA1 and FOXK2 were less dramatic than FOXM1, it is likely that these effects are biologically significant, and in part account for the anti-cancer activity of NB compounds." (PMID 38704607, 2024). "To further examine how REV-ERBα regulates FOXA1 cistrome, we ectopically expressed REV-ERBα in the cancer cells." (PMID 39383000, 2024). "The present article describes in detail the mechanisms and clinical applications of FOXA1 and FOXA2 in organ development and differentiation, metabolic reprogramming, metabolic diseases, and cancer development." (PMID 38605023, 2024). "This article focuses on the molecular mechanisms and clinical relevance of FOXA1 and FOXA2 in steroid hormone-induced malignancies and highlights potential strategies for targeting FOXA1 and FOXA2 for cancer therapy." (PMID 38605023, 2024). "Bicluster 1 CpGs were found enriched in binding regions of TFs including GRHL2, TFAP2C, FOXA1, ER, CEBPB and NR5A2, TFs known to be important in many cancer‐related functions such as proliferation, stemness and epithelial‐to‐mesenchymal transition (EMT)." (PMID 38671580, 2024). "This work discusses the roles of FOXA1 and FOXA2 in organ development, glycolipid metabolism, hormone signaling pathway transduction, and cancer drug resistance and their functions as pioneer factor." (PMID 38605023, 2024). "Although FOXA1 and MYC had a less significant correlation with integrin genes, ERG showed an overwhelmingly positive correlation with them in pan-cancer, pointing ERG as an essential upstream TF of integrins." (PMID 39436262, 2024). "When the cells with high expression of ESR1 significantly reduced the activation of FOXA1 at the BIK promoter, preventing the expression of pro-apoptotic genes and eliminating the inhibitory effect of FOXA1 on cancer development." (PMID 38605023, 2024).
cancer (continued). "YBX1 is a well-established transcription factor that has been reported to induce the transcription of oncogenic genes, such as FOXA1, FZD7, and HOXC8 in cancers." (PMID 38491348, 2024). "FOXA1 and FOXA2 play a synergistic role in organ development, but in some cases, FOXA1 and FOXA2 have opposite effects on glulipid metabolism and cancer development." (PMID 38605023, 2024). "In addition, FOXA1 mutations altered its pioneer function and disrupted the normal luminal epithelial differentiation program, further supporting the role of genealogical plasticity in cancer progression." (PMID 38605023, 2024). "In BRCA, FOXA1 and FOXM1 mRNA were higher in cancer tissues than in precancerous tissues (P < .001, the difference was statistically significant)." (PMID 38608123, 2024). "In parallel, we showed that both FOXA1 and ZBED2 play concordant roles in preventing inflammatory response in cancer cells through STAT2 inhibition." (PMID 36944729, 2023). "Other molecules, such as FOXA1, SETD2, Hes5, C/EBP-δ, PRMT5, METTL3, Piwil1, PLK1, ERK1/2, and a series of miRNA, indirectly modulate the sensitivity of cancer cells to drugs by regulating FBXW7." (PMID 36998461, 2023). "Therefore, the lack of Foxa1/2 caused by HDAC3 ablation might have released cancer promoting effect of oestrogen." (PMID 37752418, 2023). "We demonstrate that FOXA1 is an activator and NFIB is a repressor of SRR124–134 activity and SOX2 transcription in cancer cells, revealing a co-opting of the regulatory mechanisms involved in early development." (PMID 37738673, 2023). "This is indicated in cancer cells that have GATA3 depletion, where there is decreased ESR1-binding affinity, which, in turn, decreases the expression of FOXA1." (PMID 36836779, 2023). "This pattern was also observed in patients with TNBCs compared with those with HR-positive cancers (FOXC1: FC = 3.17; 95% CI, 2.86 to 3.50; P < .001; FOXA1: FC = −4.73; 95% CI, −5.30 to −4.16; P < .001) (eFigure 6A-D in Supplement 1)." (PMID 37796506, 2023). "At present, no study has yet to disclose the relationship between MAGI2-AS3 and DUSP2, or FOXA1 and MAGI2-AS3 in cancer." (PMID 36998469, 2023). "From drop-out screens in multiple cell lines, we identified novel epigenetic modifiers for cancer cell fitness as well as the previously studied ones such as PRMT5, HDAC3, FOXA1 and LSD1." (PMID 35973998, 2022). "This shows that FOXA1 and GATA3 do maintain hypo-methylated regions in cancer compared to normal cells at a subset of their binding sites." (PMID 35331302, 2022). "This study is aimed at investigating the function and downstream regulation mechanism of forkhead-box A1 (FOXA1) in CC, which was verified as an oncogene in several cancers." (PMID 35498155, 2022). "Altogether, these data identify FOXA1 and GATA3 binding sites that correlate with DNA hypo-methylation in HCC1954 cancer cells." (PMID 35331302, 2022). "The results from western blot, immunofluorescence staining, and Transwell assays showed that FOXA1 silencing impeded the progression of EMT and invasiveness of the cancer cells." (PMID 36393971, 2022). "Our cancer genetic dependency analysis found two essential genes with a DEMETER score ≤ −0.5 in the BT-474 cell line, which correspond to FOXA1 (DEMETER Score 0.83) and GINS2 (DEMETER Score 0.69)." (PMID 36359853, 2022). "In conclusion, this work has described a novel mechanism whereby JAM-A transcriptionally regulates HER2 expression through FOXA1, and revealed an important functional relevance of JAM-A, HER2 and FOXA1 co-expression for HER2-positive cancer patient survival." (PMID 35203384, 2022). "Recent studies have shown that the ceRNA network in TC plays a regulatory role and corresponding mechanisms in the development of cancer, such as lncRNA MALAT1 function as a ceRNA via sponging miR-200a-3p to derepress the FOXA1 expression." (PMID 35913967, 2022).